GATA3 (GATA binding protein 3)
Diseases named in the same sentence as GATA3 in open-access papers (continued):
Sharing a sentence is not in itself a finding about the gene and the disease.
infection (continued). "Further validation via Western blot analysis indicated that protein expression levels of IFN-γ, IL-4, IL-6, IL-17, TGF-β, GATA-3, T-bet, RORγt, and FoxP3 were significantly increased in the Pm_OMVs-infected group at 24 hours post-infection relative to the Pm group (P < 0.01)." (PMID 41306977, 2025). "Interestingly, IFN-γ treatment resulted in prolonged type 2 activity in MLN of BALB/c mice, evident in the higher frequencies of GATA-3+ T cells at day 14 p.i. compared to untreated infection controls." (PMID 39910093, 2025). "However, the timely control of primary and challenge infection with H. p. bakeri depends on the high number of GATA-3+ CD4+ type 2 T helper cells (Th2) generated in the mesenteric lymph nodes (MLN)." (PMID 39910093, 2025). "GATA3 was positively correlated to IL6 during the whole period of infection." (PMID 37593762, 2023). "However, we also showed that a significant number of these cells, in particular CD4+ cells, co-express GATA-3 with T-bet in the steady state and during infection." (PMID 36159876, 2022). "Enrichment analysis for GO and KEGG pathways indicated immune system activation in gills at severe infection, whereas in the head kidney a broad immune suppression included deactivation of cytokines and GATA3 transcription factor responsible for T helper cell differentiation." (PMID 36296170, 2022). "On the other hand, moderate patients expressing a higher level of GATA3 may be a result of a lighter infection load." (PMID 33923155, 2021). "As expected, the frequency of GATA3+ CD4+ T cells also increased with infection." (PMID 34237106, 2021). "These patients with a severe infection may have an active Th1 response as a result of GATA3 downregulation." (PMID 33923155, 2021). "The fact that expansion of GATA3+ cells exclusively occurs after a secondary infection in the presence of IL-25 may indicate that only the simultaneous combination of signals provided by the parasite and IL-25 are able to induce the polarization to Th2." (PMID 33276813, 2020). "Firstly, GATA-3 expression is upregulated by infection of H. pylori in vitro and in vivo." (PMID 29138530, 2017). "However, in comparing numbers induced by ECTV-WT infection, both T-bet+ and GATA-3+ cell numbers were increased in all strains following infection with ECTV-IFN-γbpΔ." (PMID 25751266, 2015). "Furthermore, GATA-3-expressing CD4+ T cells started to decrease after 28 days post-infection, but their levels were maintained in the lungs of mice infected with both virulent Mtb K and H37Rv (upper-right panel)." (PMID 26675186, 2015). "Furthermore, our study also showed decreased expression of the chemokines CCL3, CCL4 and CCL5 in the liver and ileum of CCR5-/- mice along with reduced induction of the transcription factors Foxp3, T-bet and GATA-3 after infection." (PMID 25119429, 2014). "Moreover, following the emergence of GATA-3+ and T-bet+GATA-3+ cells during H. polygyrus infection in a time-resolved fashion, we detected both subsets earliest on day 6 after infection." (PMID 23976880, 2013). "Hence, the differential ALDH/RA profile of BALB/c DC compared to DC from aged-matched C57BL/6 mice complies with the distinct patterns of CCR9 expression and, consequently, recruitment of MLN-derived GATA-3+ cells to the small intestine upon infection with enteric nematodes." (PMID 39910093, 2025). "As expected, the expression of GATA-3 and T-bet was increased in T cells cultured with IL-2-IL-4 and IL-2-IL-12p70, and IL-2-IL-12-cultured T cells, but not IL-2-IL-4-cultured T cells, significantly inhibited Mtb growth in macrophages compared to the infection control." (PMID 34299161, 2021). "At the late phase of infection, the increase in the levels of cytokines typical for Th1 Th2 and Th17 responses indicates lack of polarization of the immune response and was consistent with the increase in the mRNA levels of the transcription factors Tbet, GATA3 and RORγC." (PMID 26512987, 2015).
infection (continued). "These analyses suggest that expression of Gata3 (a master transcription factor involved in the differentiation of Th2 cells) can, in some individuals, be a marker for a physiological programme of tolerance to macroparasite infection, with implications for body condition, fecundity, and survival." (PMID 25004450, 2014). "Although it is possible that larger parasite numbers in the alt-transfection system may in themselves alter macrophage gene expression, parasite densities were only slightly shifted at 24 h, when GATA-3 expression was markedly different in wildtype and transfected cell infections." (PMID 15788098, 2005). "Infection of mice with B. malayi confirmed that expression of both GATA-3 and SOCS-1 is increased following infection in both macrophage-enriched adherent cells and lymphocyte enriched non-adherent cells." (PMID 40565065, 2025). "Complementary ELISA data demonstrated a significant augmentation in the secretion of cytokines IFN-γ, IL-4, IL-6, IL-17A, TGF-β, GATA-3, T-bet, IL-10, and TNF-α in the Pm_OMVs-infected group relative to the Pm group at 24 hours post-infection (P < 0.01)." (PMID 41306977, 2025). "The accelerated small intestinal homing of type 2 cells seen in infected BALB/c compared to C57BL/6 mice correlated with the higher CCR9 expression by GATA-3+ cells and the higher ALDH activity of DC isolated from MLN of BALB/c mice early during infection." (PMID 39910093, 2025). "Phenotypic assessment of Tbet+ cells after neonatal and adult infection showed most cells were in the effector state (eg CD44+CD62L–), while neonatal GATA3+ cells were less likely to be activated." (PMID 40280180, 2025). "We found that levels of TBX2, GATA3, RORC, SPI1, and BCL6 in the livers of infected rabbits were elevated on days 5 and 15 post-infection (PI)." (PMID 37593762, 2023). "Consistent with our earlier data in naive mice, at day 10 post-infection, TDD-fed mice had significantly expanded RORγt+ Treg cells with increased proliferation and reduced Gata3+ Treg cells." (PMID 36840944, 2023). "On day 5 PI, GATA3 mRNA and IL4 significantly increased after the infection compared to the control." (PMID 37593762, 2023). "By day 4 post-infection, we detected activated virus-specific CD8+ and CD4+ T cells in the infected skin, with most gDT-II CD4+ T cells displaying Th2 (GATA3+) and Th17 (RORγt+) phenotypes." (PMID 37371900, 2023). "The proportion of TH2 (CD4+ CD44+ FoxP3- Tbet- GATA3+) cells was significantly lower than the TH1 cells, and ranged from 4% - 11% of the activated CD4+ T-cells in the UgCl223 infection." (PMID 35186781, 2021). "GATA3+ Treg cells express ST2 by which they can sense epithelial derived IL‐33, an alarmin which is produced by intestinal epithelial cells upon infection." (PMID 34369649, 2021). "Subsequently, the expression of GATA-3, the transcription factors of Th2 cells, was up-regulated by 10-fold at 3 days post-NNV infection." (PMID 33467734, 2021). "Our results show that after 48 hours of infection, CIS results in an up-regulated expression of GATA-3 in the oviduct, uterine horns, and cervix lysates." (PMID 32413046, 2020). "To determine how long the effect of stress persists, we compared the gene expression of T-bet and GATA-3 or secretion of IFN-γ and IL-4 by CD4+ T cells at two- or 11-days post-infection." (PMID 32413046, 2020). "Hepatitis B virus (HBV) releases HBc and HBx proteins to promote the expression of transcription factors GATA-2 and GATA-3 after infection, and GATA-2 and GATA-3 specifically inhibit MICA/B expression by directly binding to the promoter region of MICA/B." (PMID 30813924, 2019). "Steady state GATA-3 expression by Treg and the expansion of GATA-3+ Treg upon infection was similar in mLN of SPF and GF mice." (PMID 30349532, 2018). "GATA-3+Treg expanding in mLN of infected SPF and GF mice clearly dominated the IL-10-expressing Treg pool in both groups upon infection." (PMID 30349532, 2018).
infection (continued). "In contrast, in Cftr−/−mice, both types of ILC2 steadily increased throughout the infection along with the expression of the ILC2 transcription factors, Rora, and Gata3 and the production of ILC2 effector cytokines, IL-5 and IL-13." (PMID 28090087, 2017). "Interrupting IL-4Rα expression prior to the secondary infection resulted in reduced proportions and total numbers of CD4+CD44+ T cells expressing Gata-3 compared to control mice given vegetable oil." (PMID 28651009, 2017). "During infection, 11% of total CD4+ T cells in MLN of B6 mice were GATA3+ while 12% of total CD4+ T cells expressed Foxp3 in infected Irf8-/- mice." (PMID 28968468, 2017). "We observed increased mRNA levels of the Th1/Th2/Th17-related major transcription factors Tbet, GATA3, and RORγC and diminished expression levels of Foxp3, CCR6 and PD-L1 after 2 weeks of infection." (PMID 26512987, 2015). "We found no activation or even reduction in base-line expression for multiple molecules (IL-7, IL-4, IL-13, GATA3, ROR-γt, and CXCL12) at 2, 6 and 10 days post-infection." (PMID 25254971, 2014). "Gata3 ChIP‐seq was carried out on naïve (CD44loCD62Lhi) OTIs, after in vitro activation in the presence of IL‐4 or Notch signaling (OP9‐DL1), or primary effector OT‐Is isolated directly ex vivo 10 days after adoptive transfer and infection with A/HKx31‐OVA." (PMID 40012375, 2025). "As expected from our earlier studies, IFN-γ applied to BALB/c mice for the first 5 days of infection resulted in stronger Th2/1 hybrid responses, evident in the more prominent IFN-γ production and diminished IL-4 expression of GATA-3+ T cells isolated from IFN-γ treated mice at day 6 post infection." (PMID 39910093, 2025). "Nevertheless, it is tempting to speculate that Gata3 and Runx2 may combine to help shape CD8+ T cell responses to infection." (PMID 40012375, 2025). "At 72 hours post-infection, protein levels of IL-17, IFN-γ, T-bet, RORγt, and IL-6 were significantly decreased, whereas TGF-β, GATA-3, IL-4, and FoxP3 protein expression was significantly upregulated in the Pm_OMVs-infected group compared to the Pm group (P < 0.01)." (PMID 41306977, 2025). "Conversely, at 72 hours post-infection, the secretion of IL-6, IL-17, T-bet, TNF-α, and IFN-γ was significantly diminished (P < 0.01), while levels of TGF-β, GATA-3, IL-10, and IL-4 were significantly elevated in the Pm_OMVs-infected group compared to the Pm group (P < 0.01)." (PMID 41306977, 2025). "Cluster 3, which identified genes upregulated at day 7 post-infection, was highly enriched for T cell responsive genes, including those involved in T cell activation, lymphocyte proliferation, and TCR signaling, e.g. CD3D/E/G, CD8A/B, CD28, CD40LG, and GATA3." (PMID 38950078, 2024). "Elevated Treg cell counts in RelBΔDC mice were maintained during infection and Treg cells of RelBΔDC mice did not acquire Th2-like capacities despite elevated GATA3 expression and a strong Th2 cell-biased microenvironment." (PMID 39443450, 2024). "TH1- and TH2-related transcripts included Nfatc1, Cd4, Runx3, and Gata3, suggesting that TH1 cells may be a significant contributor to interferon-gamma (IFNγ) production during infection in the adipose tissue." (PMID 37923768, 2023). "We also assessed ILC2 responses in MLNs from naive and infected mice, defined as lineage-negative (Lin−) CD45+ICOS+GATA3+ cells; both the percentages and total numbers were greatly reduced in MIF-deficient mice, with no increase apparent following infection." (PMID 35288645, 2022). "We observed that CD4+GATA3+ T cells increased significantly in the MLN after both primary and challenge infections compared to uninfected mice, but their numbers were significantly lower after primary infection compared to challenge infection." (PMID 35757733, 2022). "The percentage of CD4+GATA3+IL-4+ Th2 cells and CD4+CXCR5+ Tfh cells, and IL-4 production in the 8-week-old mice significantly increased on day 5 and day 10 after P. yoelii 17XNL infection." (PMID 33430765, 2021).
infection (continued). "In this study, the expression of T-bet and IFN-γ1 showed a significant increase, and subsequently STAT-1 expression was up-regulated at 1 day post-infection with NNVand immuno-stimulation with KLH, whereas slight increases in IL-13 and GATA-3 expression were noted at 3 days post-NNV infection." (PMID 33467734, 2021). "Besides, we also detected the expressions of T help cell differentiation-related transcription factors including TBX21 (T-bet), GATA3, and Foxp3 between CD4+CD8low+ double-positive T cells and CD8+ single-positive T cells after ALV-J infection." (PMID 34858872, 2021). "Primary infection did not elicit hyperplasia of tuft cells and only elicited a slight increase in GATA3+ cells populations, although this increase rapidly returned to basal values." (PMID 33276813, 2020). "While WT mice showed a significant increase in absolute numbers and frequency of GATA3+CD4+ T cells upon infection, Il17a-KO mice had a significantly lower frequency of GATA3+CD4+ T cells and failed to upregulate these cells on d7pi compared with WT controls." (PMID 32636457, 2020). "Transgenic mice that overexpress GATA-3 have been developed and are reported to be more vulnerable to Candida albicans infection, suggesting that the overexpression of GATA-3 induces a shift to a Th2 response during infection." (PMID 32326041, 2020). "In the spleen, elevated frequencies of GATA3+ CD4+ T cells were detected at 6 and 8 weeks post infection (part C), and at all three time points in the mesenteric nodes (part D), with frequencies again increasing as the infection progressed." (PMID 30653492, 2019). "Consequently, we calculated the Th1/Th2 ratio based on the relative expression levels of GATA3, IL-4, T-bet, and IFN-γ at days 10 and 28 after infection." (PMID 29535708, 2018). "Reflecting their high frequencies in the total siLP Treg population, GATA-3+Treg dominated in the small intestinal IL-10+ population irrespective of microbial and nematode-infection status." (PMID 30349532, 2018). "In contrast, T. gondii-primed T cells did not express significant amounts of the transcription factors Rorγt and Gata3 with or without a secondary infection, which excludes the role of long-lived Th17 and Th2 cells in our model." (PMID 28439500, 2017). "This contrasts with GATA3 expression in the ALN where there was no differential expression at the site of immune response induction three months after initial infection and during the mature phase of the immune response." (PMID 27973603, 2016). "On the other hand, ECTV-IFN-γbpΔ infection did not significantly change T-bet+ or GATA-3+ cell numbers in GKO strains compared to those in WT mice." (PMID 25751266, 2015). "Our longitudinal analyses suggest, moreover, that rather than being a mere correlate, elevated Gata3 expression was triggered by macroparasite infection and preceded the life history readjustments." (PMID 25004450, 2014). "We then tested whether GATA-3 and SOCS-1 are up-regulated by live infection with B. malayi larvae in vivo." (PMID 15788098, 2005). "Accordingly, both types of GATA-3+ cells appeared to home to the infected gut with similar efficiency, evident in the congruent proportions of Th2 and Th2/1 cells comparing the inductive (MLN) and effector site (siLP) on an individual basis at day 6 post-infection." (PMID 39910093, 2025). "The decrease in GATA‐3 expression is unlikely to be due to a loss of Th2 cells, as 20–60% of the PleC CD4+ T cells remain IL‐4gfp+ Th2 cells during the hypo‐responsive phase of infection." (PMID 40755147, 2025). "One hypothesis could link GATA3 with the oncogenic potential of EBV since GATA3 was expressed in all but one GC-lymphoblastoid B-cell lines (LCL), indicating that EBV-infection can induce deregulation of expression of transcription factors that are involved in cell lineage decisions." (PMID 38534975, 2024).
infection (continued). "The T-bet/GATA-3 ratio, a marker of Th1/Th2, was not altered during acute infection, but was significantly increased when the infection became chronic, suggesting more bias towards a Th1-mediated inflammatory response during late infection." (PMID 29216911, 2017). "Interestingly, GATA-3-expressing CD4+ T cells, which are considered Th2-type T cells, accumulated more quickly and to higher levels than T-bet-expressing CD4+ T cells, regardless of the Mtb strain, and the levels peaked at 28 days post-infection." (PMID 26675186, 2015). "However, at 72 hours post-infection, the expression of IL-17, IFN-γ, T-bet, RORγt, and IL-6 genes was markedly reduced in the Pm_OMVs-infected group compared to the Pm group (P < 0.01), whereas the expression levels of TGF-β, GATA-3, IL-4, and FoxP3 were significantly increased (P < 0.01)." (PMID 41306977, 2025). "Infection-induced TIGIT+ repair Treg cells also did not express the tissue Treg cell markers ST2, KLRG1 or GATA3 at the transcriptional or protein level." (PMID 41094201, 2025). "Infection studies using GATA-3-/- mice have not been possible, as the germline deletion of GATA-3 often results in embryonic lethality." (PMID 32326041, 2020). "Only one study also measured the expression of transcription factors T-bet, Gata-3 and Foxp3 in CD4+ T cells following STM infection but the results were not fully conclusive." (PMID 33584671, 2020). "Here, using T-bet-tg C57BL/6 mice and Gata3-tg C57BL/6 mice, we demonstrated that overexpression of T-bet, but not Gata3, in T cells was detrimental in TMEV infection." (PMID 28874814, 2017). "In this study using T-bet-tg mice and Gata3-tg mice on the resistant C57BL/6 mouse background, we demonstrated that T-bet, but not Gata3, overexpression in T cells was detrimental in neurotropic TMEV infection." (PMID 28874814, 2017). "Following either systemic or intravaginal infection, almost all PmpG-1-specific CD4 T cells expressed T-bet while no GATA3 expression was detected." (PMID 24204262, 2013). "Following infection, the carrier lambs had significantly (P < 0.05) higher levels of ITNL2 on day 3 and GATA3 on day 7 compared to the non-carriers." (PMID 21385411, 2011). "Our subsequent histological evidence confirmed this hypothesis: no GATA3+ ILC2 signals were observed in either the peripheral or core regions of the injury after TBI, even following AAV‐IL33 infection." (PMID 40605604, 2025). "Naïve and nematode-infected GF mice display a reduction in RORγt+ Treg in the gut and gut-draining lymph nodes, while GATA-3+ Treg expanded similarly in SPF and GF mice and formed the major IL-10 producing Treg subset upon infection irrespective of the microbial status." (PMID 30349532, 2018).